TLR4 (toll like receptor 4)
Diseases named in the same sentence as TLR4 in open-access papers (continued):
Sharing a sentence is not in itself a finding about the gene and the disease.
Sepsis (continued). "Larger studies are needed in order to determine the extent of elevated TLR4 activation in sepsis patients and the impact of this activation on the outcome." (PMID 36230982, 2022). "The TLR4 signaling cascade is critically involved in the development and progression of inflammatory responses during sepsis." (PMID 35335387, 2022). "Beyond that, platelet TLR4 has been widely investigated in the context of classical inflammatory diseases, such as sepsis, pneumonia and Crohn’s disease." (PMID 35741086, 2022). "Increased TLR4 expression has been reported to aggravate sepsis-induced inflammation in mouse model." (PMID 35510365, 2022). "At the same time, upregulation of TLR4 was significantly found in ileal tissue of the sepsis group (P < 0.0001)." (PMID 36088483, 2022). "For example, blockade of TLR4 was employed in a clinical trial in which sepsis patients were treated with eritoran, a synthetic TLR4 antagonist that reduced LPS-dependent activation of TLR4." (PMID 35634305, 2022). "To conclude, we established a diagnostic assay that is able to quantify the phosphorylation of TLR-4 in cell culture and in clinical samples of sepsis patients." (PMID 36230982, 2022). "The AUROC of TLR4 in the diagnosis of sepsis was 0.808 (95% CI 0.735–0.882), with the sensitivity and specificity of 0.592 and 0.969, respectively." (PMID 35844488, 2022). "Recently, WISP1 was shown to promote the inflammatory response via TLR4/CD14 pathways in sepsis-induced lung injury." (PMID 36352407, 2022). "In the course of sepsis, macrophages were activated by LPS through the TLR4/MD2 and releasing the inflammatory factors." (PMID 35281916, 2022). "magnesium sulfate ameliorates sepsis-induced diaphragm dysfunction in rats via inhibiting HMGB1/TLR4/NF-κB pathway." (PMID 35720285, 2022). "EA at ST36 prevented sepsis from worsening by inhibiting inflammation and apoptosis, which correlated with the regulation of the TLR4/NF-κB/MyD88 signaling axis and modulation of the intestinal flora." (PMID 35722155, 2022). "From all animal models, we demonstrated the gut translocation of bacteria-free DNA in sepsis with LPS-bacterial DNA synergy, possibly through the simultaneous TLR-4 and TLR-9 activation on macrophages." (PMID 35163830, 2022). "The inflammatory response to both traumatic injury and sepsis/endotoxemia involves Toll-like receptor-4 (TLR4)." (PMID 35663944, 2022). "As therapeutic options to specifically treat the dysregulated immune response in sepsis have been largely unsuccessful thus far, the TLR4 inhibitors were viewed as a good approach to reduce the mortality in sepsis." (PMID 36230982, 2022). "To conclude, in this study we show the feasibility of a PLA assay to study the activation of TLR4 in cell culture and the PBMCs of sepsis patients." (PMID 36230982, 2022). "The antimicrobial role of NETs has been confirmed by studies that showed the ability of NETs to prevent microbial dissemination as well as the interaction between NETs and platelet Toll-like receptor 4 (TLR4) during sepsis." (PMID 35884400, 2022). "The strong immuno-suppressive effects of ginsenoside Rg6 on Toll-like receptor 4–induced systemic inflammatory responses, such as liposaccharide-induced septic shock and cecal ligation and puncture-induced sepsis, should be mentioned." (PMID 36438846, 2022). "Butyric acid reduces the nuclear NF-κB activity, IL-6 and TNF-α levels, and lung tissue neutrophil infiltration by inhibiting the expression of high mobility group protein 1, TLR4, or histone deacetylase to reduce sepsis-related ALI." (PMID 35003009, 2021). "Their group reported the protective effect of intraperitoneal injection of the TLR4 or TLR7/8 agonist 24 h prior to the initiation of sepsis, resulting in increased survival and reduced bacteremia via enhanced peritoneal neutrophil recruitment." (PMID 34945120, 2021).
Sepsis (continued). "Generation of ROS-independent NETs via Toll-like receptor 4 (TLR4) has also been demonstrated in platelet-stimulated NETosis in the course of sepsis." (PMID 34445556, 2021). "Quercetin was reported to protect mice from LPS-induced sepsis by inhibiting TNF-α and IL-1β expressions, NF-κB activation, and apoptosis and proposed to prevent myocardial dysfunction through the TLR4/NF-κB signaling pathway during sepsis." (PMID 34938184, 2021). "As an important mediator of sepsis, lipopolysaccharide (LPS) activated macrophages via toll-like receptor 4 (TLR4) pathways in ALI." (PMID 34093568, 2021). "Given the importance of TLR4 signaling in inflammation and immunity, including sepsis, it will therefore be interesting to assess its functions in other cell types and disease processes." (PMID 34543116, 2021). "The HMGB-1, MyD88, TLR4, and NF-κB mRNA expressions were upregulated in the sepsis groups than in the NC group." (PMID 33859538, 2021). "Sepsis and LPS were shown to induce HSCs impairment by decreasing their self-renewal, repopulating, and myeloid differentiation ability by a direct TLR4 signaling." (PMID 34367170, 2021). "Collectively, our study shows that Fer-1 improved sepsis-induced cardiac dysfunction and alleviated cardiac ferroptosis and inflammation which is at least partially by inhibiting the TLR4/NF-κB signaling pathway." (PMID 34787054, 2021). "Currently, a TLR4 antagonist initially developed for sepsis therapy is being clinically tested for the treatment of allergic diseases." (PMID 34442794, 2021). "It has been reported that several lncRNAs are involved in the development of hyperinflammatory state in sepsis through the TLR4 signaling pathway." (PMID 34055659, 2021). "It was reported that NEAT1 interacts with the axis of Let-7a/TLR4 to promote inflammatory responses, thereby accelerating the progression of liver injury involved in sepsis." (PMID 34972503, 2021). "The finding of surface expression of HMGB1 in LPS-activated platelets via TLR4 offers a contribution to the study of translational sepsis research." (PMID 34235204, 2021). "After polymicrobial sepsis, expression of TLR4 increases in renal tubules, glomeruli and vasculature and circulating endotoxins have been detected in these locations." (PMID 33467524, 2021). "CD14 was a receptor of LPS and was reported to mediate the occurrence and development of sepsis through the TLR4-NFκB pathway." (PMID 34938184, 2021). "For example, 1) TAK1: it was proved to play important roles in the inflammatory response mediated by TLR4, which had been regarded as a method in controlling sepsis." (PMID 34938184, 2021). "Sepsis upregulated the Toll-like receptor 4/nuclear factor-kappa B axis in lung and renal tissues, as well as increasing inflammatory cytokine levels and macrophage infiltration; all of those effects were attenuated by GP." (PMID 33723330, 2021). "During sepsis, increased cytokine levels inhibit intestinal cell regeneration and promote apoptosis in a TLR4-dependent manner." (PMID 35003009, 2021). "In sepsis conditions, TLR2−/−, TLR4−/− and MyD88−/− deficient mice, present reduced renal apoptotic rates compared to wild type mice, favoring clearance of damaged cells." (PMID 33467524, 2021). "Further, experiments with myocyte-specific deletions of TLR2 and or TLR4 are needed to state that these receptors mediate sepsis-induced muscle atrophy in vivo." (PMID 34572540, 2021). "IRF3 signaling, one component of the TLR4 signaling pathway, has been highlighted to contribute to sepsis pathogenesis." (PMID 33869780, 2021). "Clinical studies targeting TLR4 signaling as a therapeutic approach for sepsis and septic shock have brought several compounds and antibodies to clinical trials, with unsuccessful results." (PMID 33841413, 2021). "NF-κB is an important downstream inflammatory effector of TLR4 and is upregulated in the myocardium during sepsis." (PMID 34787054, 2021).
Sepsis (continued). "sTLR4 acts as a potent inhibitor of TLR4-mediated inflammation, and in humans, its serum levels are elevated in different conditions, like sepsis and some inflammatory diseases." (PMID 33808205, 2021). "TLR4, the main inflammatory kidney injury marker in sepsis and SIRs 21, 46, was extensively expressed in tubules in the ST and ST+Sham BAL groups compared with that in the ST+BAL group." (PMID 34335954, 2021). "An exaggerated and uncontrolled pro-inflammatory signaling triggered by TLR4 during infection can lead to sepsis, septic shock, and death." (PMID 33057840, 2021). "The high expression of some proteins, such as TLR2, TLR3, and TLR4, have been demonstrated to play a crucial role in sepsis-induced acute injury of the lungs, kidneys, and intestine." (PMID 34938184, 2021). "Due to no available human monoclonal antibody to block RAGE at present time, this in vitro human study was designed to determine the role of TLR4 inhibition in apoptosis in patients with sepsis." (PMID 34733114, 2021). "Further studies including knockout models in mice or blocking of TLR4-signaling pathways would confirm the translational significance of dogs as a naturally occurring model for sepsis." (PMID 34235204, 2021). "Platelet TLR-4, for example, has been shown to induce the formation of Neutrophil Extracellular Traps (NETs) in sepsis." (PMID 34831457, 2021). "The discovery of TLRs in humans, and the early recognition of TLR-4 as the receptor that signals LPS bioactivity were major breakthroughs not only in the field of immunology but also in sepsis." (PMID 33803628, 2021). "On the other hand, an experimental exclusion of TLR4-triggered signaling during low-grade polymicrobial sepsis resulted in an impaired bacterial clearance and thereby worsened organ injury leading to a higher mortality of mice." (PMID 33057840, 2021). "Recent work has described the activation of both TLR2 (recognition of bacterial cell wall components) and TLR4 (recognition of lipopolysaccharide) as a consequence of bacterial mediated sepsis leading to ARDS." (PMID 33471802, 2021). "In summary, these findings imply that Fer-1 improved sepsis-induced cardiac dysfunction at least partially via the TLR4/NF-κB signaling pathway." (PMID 34787054, 2021). "TLR4, one member of toll-like receptors (TLRs), has been found to exert a prominent effect on sepsis occurrence and maintenance." (PMID 34489703, 2021). "The TLR4-NF-κB axis plays a central part in the inflammatory response and apoptosis of renal epithelial cells during sepsis-induced acute kidney injury." (PMID 34076840, 2021). "In a murine model of LPS TLR4 activation-induced sepsis, signaling through the downstream adaptors MYD88 and TRIF result in permanent alterations to the HSC transcriptional programs." (PMID 34356379, 2021). "The re-defined role of TLR4 provides a plausible explanation for the failure of using the TLR4 antagonist Eritoran to treat patients with sepsis." (PMID 34858408, 2021). "TLR4 appears to be a promising therapeutic target in COVID-19, and since TLR4 antagonists have been previously trialled in sepsis and in other antiviral contexts, we propose the clinical trial testing of TLR4 antagonists in the treatment of severe COVID-19." (PMID 33505220, 2021). "Severe COVID-19, ALI/ARDS and sepsis patients are all characterized by the activation and increased expression of TLR2, TLR4 and NOD2 (and sometimes NOD1, as well) and their associated synergisms (which are quite numerous)." (PMID 33672738, 2021). "In the study of sepsis, upregulation of platelet-TLR4 was most evident on admission and persisted until day 5 of hospitalization." (PMID 32858930, 2020). "The incidence of sepsis was associated with TLR2 Arg753Gln: AG genotypes, A allele and TLR4 Asp299Gly: CT genotype and C allele as compared to other genotypes and alleles." (PMID 33247673, 2020).
Sepsis (continued). "The physiological importance of caspase-11 inflammasomes was determined in mice pre-treated with poly(I:C), which developed TLR4-independent but caspase-11-dependent sepsis." (PMID 33042141, 2020). "In conclusion, puerarin exhibited a strong anti-sepsis effect by preventing cell death in organs and by promoting anti-inflammatory M2 differentiation in macrophages, likely via the suppression of TLR4/NF-κB/JNK pathways." (PMID 32457606, 2020). "Mechanistically, β3 was shown to upregulate CD14, a key factor that enhances toll-like receptor 4 (TLR4)-LPS interactions during the inflammatory response to sepsis." (PMID 33195249, 2020). "The intracellular and extracellular components of the TLR4 signaling cascade are potential therapeutic targets for the treatment of acute inflammation disorders like sepsis where there is excessive cytokine secretion." (PMID 32076015, 2020). "This evidence suggests that sesamin can suppress the HMGB1/TLR-4/IL-33 signalling pathway, the activation of which is possibly involved in the in vitro LPS-induced sepsis model." (PMID 32893702, 2020). "It has been reported that activation of TLR4 induces inflammation and aggravates cardiac dysfunction in severe sepsis, while knockout of the TLR4 gene improves sepsis-induced cardiac dysfunction." (PMID 32908632, 2020). "Here we show that in a mouse model of acute sepsis, bacterial lipopolysaccharides (LPS) suppress medullary erythroblastic islands (EBIs) and erythropoiesis in a TLR-4- and MyD88-dependent manner with concomitant mobilization of HSCs." (PMID 33123170, 2020). "Platelet TLR4 is involved in inducing NETs in mice and humans; moreover, it plays prominent roles in sensing high circulatory LPS levels during sepsis and in neutrophil-mediated pathogen clearance." (PMID 32600436, 2020). "Extracellular LPS was thought to induce sepsis exclusively via the secretion of proinflammatory cytokines by binding to cell-surface toll-like receptor 4 (TLR4)." (PMID 32332915, 2020). "We assume that this is in part the case with the majority of our patients exhibiting septic shock: in those patients, AB strains escaped innate immune clearance and initiated a TLR4 mediated sepsis." (PMID 32093299, 2020). "Our results thus provide a rationale to test the effects of TLR4 inhibitors on sepsis-induced muscle wasting and long-term survival in clinical trials." (PMID 31959927, 2020). "Our research team has shown that corilagin exerts an anti-inflammatory effect in sepsis through downregulation of expression of TLR4, MyD88, TRIF, and TRAF6 in the TLR4 signaling pathway." (PMID 32849545, 2020). "It has been shown that p38 MAPK pathways play a key role in the inflammatory response in sepsis-induced acute lung injury via lipopolysaccharide-induced TLR-4 signaling." (PMID 32793609, 2020). "It has been reported that platelet TLR4 can activate blood neutrophils during sepsis to form NETs in order to ensnare bacteria." (PMID 32528475, 2020). "Gram-negative bacteria release LPS which is recognized by toll-like receptor 4 (TLR4) on macrophages ultimately triggering the activation of cytokines that ultimately leads to inflammation and sepsis." (PMID 32582649, 2020). "Sesamin improved the 7-day survival rate of septic mice, suppressed the inflammatory response in sepsis through the HMGB-1/TLR4/IL-33 signalling pathway, and further alleviated intestinal injury." (PMID 32893702, 2020). "The results of this study show that high expression of NEAT1 is associated with severity of sepsis and knockdown of NEAT1 attenuates LPS-induced inflammatory response in macrophages, possibly by acting as a ceRNA of miR-17-5p to regulate TLR4." (PMID 32099901, 2020). "The occurrence of sepsis is related to the TLR4/MyD88 signaling pathway, which activates the secretion of cytokines associated with cardiac dysfunction in adult mammalian heart and in mice." (PMID 32423469, 2020).
Sepsis (continued). "Toll-like receptor 4 (TLR4) activated by bacterial endotoxin-like lipopolysaccharide (LPS) is required for initiating inflammatory response and responsible for sepsis." (PMID 32099901, 2020). "In sepsis patients, platelet toll-like receptor 4 has been shown to induce platelet-neutrophil aggregation and subsequent NET-formation." (PMID 32326325, 2020). "TLR4 signaling can be activated in sepsis, but also in sterile inflammation, trauma, and autoimmune diseases." (PMID 33224150, 2020). "This inflammation was originally thought to be entirely TLR4 dependent, however evidence is growing that TREM-1 is important in sepsis-associated cardiac inflammation." (PMID 33276725, 2020). "The TLR4 signaling pathway is activated and mediates the release of inflammatory mediators during sepsis." (PMID 32153412, 2020). "The most typical mechanism to describe the initiation of sepsis is the activation of TLR4 by LPS, which is a major components of the outer membrane of gram-negative bacteria." (PMID 33013905, 2020). "Along similar lines, genipin and artesunate have also been shown to protect against sepsis by mitigating TLR4 activation through MyD88 downregulation." (PMID 33139717, 2020). "MD2 is a complex that binds to TLR4, mediates the LPS-induced inflammatory response, playing an important role in sepsis and malignant tumors." (PMID 33192512, 2020). "Lipopolysaccharide (LPS) is the main stimulus to induce sepsis, which can activate inflammatory cells through multiple pathways such as toll-like receptor 4 (TLR4) and promote the expression of inflammatory factors." (PMID 32432055, 2020). "Physical exercise is capable of promoting physiological alterations and modulating inflammatory responses in the infectious process through multiple parameters, including the toll-like receptor (TLR)-4 pathway, which is the main LPS signaling in sepsis." (PMID 32765291, 2020). "Some potential therapeutic methods have been demonstrated in sepsis treatment by inhibiting the TLR4 signaling." (PMID 32455124, 2020). "Our data show that uPAR can interfere with innate immunity response via TLR4 and this mechanism represents a potentially important target in inflammation and sepsis therapy." (PMID 33362762, 2020). "Western blot analysis further confirmed that miR-22-3p overexpression significantly down-regulated the expression of PTEN, HMGB1, p-p65 and TLR4 in sepsis-induced acute renal injury rat models." (PMID 32412059, 2020). "In this regard, different peptides have been created to inhibit the TLR4 signaling pathway in animal models of sepsis and mastitis with good results." (PMID 32164729, 2020). "New drugs developed to inhibit TLR4 activity are already in various phases of preclinical and clinical trials for treating acute and chronic inflammation, colitis, sepsis, chronic pain, and addiction withdrawal." (PMID 32397494, 2020). "Obviously, microbial structures, such as LPS or CpG, flood the host system during sepsis, and are able to polyclonally activate B cells via their appropriate receptors (TLR4 or TLR9)." (PMID 32425951, 2020). "S100A8/A9 is an endogenous ligand of Toll like receptor 4 (TLR-4), which is related to sepsis and endotoxemia and plays an important role in innate immunity." (PMID 32680574, 2020). "TLR4 antagonists have been developed to beneficially block TLR4 signaling in various diseases such as sepsis, septic shock, lung inflammation, and RA." (PMID 31973752, 2020). "In conclusion, this study showed that BIG1 plays a crucial role in mediating the activation of TLR4-MyD88 signaling pathways through its interaction with ARF3 during the pathological process of sepsis." (PMID 32415087, 2020). "TLR4 is one of the widely studied TLRs, which acts as a key molecule in the regulation of inflammatory response in sepsis." (PMID 32455124, 2020). "Lipopolysaccharide (LPS) challenge is a widely used model to study leukocyte programming in sepsis with the assumption that TLR4 is the main driver of inflammation." (PMID 33336149, 2020).